ARMH3 (armadillo like helical domain containing 3)
Description:
Involved in GBF1 recruitment, Golgi maintenance and protein secretion.
Synonyms: C10orf76; FLJ13114; DGARM
Tractability: Antibody: UniProt predicts a signal peptide or a membrane-spanning region. PROTAC: ubiquitination databases record sites on it.
Gene: Protein-coding gene on chromosome 10 (101,845,599 to 102,056,258, reverse strand). Ensembl gene ENSG00000120029.
Subcellular location: Golgi apparatus membrane; Cytoplasm
Subcellular location (Human Protein Atlas): Vesicles
Gene Ontology:
Molecular function: protein binding
Biological process: regulation of Golgi organization
Cellular component: cytoplasm; cytosol; Golgi membrane; Golgi apparatus; perinuclear region of cytoplasm
Genetic constraint (gnomAD): Loss-of-function variants: 54 observed, 88.59 expected, observed/expected ratio (o/e) 0.61, 90% interval 0.49 to 0.76. The upper end of that interval is the gene's LOEUF score, 0.76, which puts it in group 3 of 6, group 1 being the genes least tolerant of losing a copy. Missense variants: 611 observed, 784.51 expected, observed/expected ratio (o/e) 0.78, 90% interval 0.73 to 0.83. Synonymous variants: 254 observed, 281.3 expected, observed/expected ratio (o/e) 0.9, 90% interval 0.81 to 1.
Homologues: Orthologues: chimpanzee ARMH3 (100% identical), dog ARMH3 (99% identical), macaque ARMH3 (99% identical), pig ARMH3 (99% identical), mouse Armh3 (99% identical), rat Armh3 (98% identical), guinea pig ARMH3 (96% identical), rabbit ARMH3 (96% identical), tropical clawed frog armh3 (92% identical), zebrafish armh3 (85% identical), Drosophila melanogaster CG8379 (48% identical).
Diseases named in the same sentence as ARMH3 in open-access papers:
ARMH3 is named in the same sentence as 3 diseases in open-access papers, as found by Europe PMC text mining. Sharing a sentence is not in itself a finding about the gene and the disease. The quoted sentences say what the papers report.
lung carcinoma (1 paper, 2025). "To determine which proteins are responsible for recruiting PI4KB in lung cancer cells, we conducted a biotin proximity labeling assay using TurboID-fused PI4KB or PI4K2A as the baits, revealing ACBD3 and ARMH3 as major PI4KB binding partners." (PMID 40189704, 2025).
ARMH3 also shares sentences with these, for which no sentence is quoted: enterovirus infection (1 paper); tumor (1).